DDR1 (discoidin domain receptor tyrosine kinase 1)
Description:
Tyrosine kinase that functions as a cell surface receptor for fibrillar collagen and regulates cell attachment to the extracellular matrix, remodeling of the extracellular matrix, cell migration, differentiation, survival and cell proliferation. Collagen binding triggers a signaling pathway that involves SRC and leads to the activation of MAP kinases. Regulates remodeling of the extracellular matrix by up-regulation of the matrix metalloproteinases MMP2, MMP7 and MMP9, and thereby facilitates cell migration and wound healing. Required for normal blastocyst implantation during pregnancy, for normal mammary gland differentiation and normal lactation. Required for normal ear morphology and normal hearing (By similarity). Promotes smooth muscle cell migration, and thereby contributes to arterial wound healing. Also plays a role in tumor cell invasion. Phosphorylates PTPN11.
Synonyms: CAK; EDDR1; NEP; NTRK4; PTK3A; RTK6; TRKE; CD167; DDR; HGK2; MCK10; PTK3
Tractability: Small molecule: a structure with a bound ligand is known; a high-quality ligand is known; it belongs to a druggable protein family. Antibody: UniProt places it where antibodies can reach, with high confidence; its Gene Ontology location is reachable by antibodies, with high confidence; UniProt predicts a signal peptide or a membrane-spanning region; the Human Protein Atlas places it where antibodies can reach. PROTAC: ubiquitination databases record sites on it; its protein half-life has been measured; a small molecule that binds it is known.
Target class: Protein Kinase; Enzyme; Kinase; Tyrosine protein kinase DDR family; TK protein kinase group
Chemical probes: ALW-II-49-7 (high quality), BAY-826 (high quality), D2202-1 (high quality), DDR-IN-1 (high quality), DDR1-IN-2, PD084238, SR-302 (high quality)
Gene: Protein-coding gene on chromosome 6 (30,876,421 to 30,900,978, forward strand). Ensembl gene ENSG00000204580.
Subcellular location: Cell membrane (Isoform 1); Cell membrane (Isoform 2); Secreted (Isoform 3); Cell membrane (Isoform 4)
Subcellular location (Human Protein Atlas): Plasma membrane; Cytosol; Nucleoplasm
Pathways (Reactome):
Extracellular matrix organization: Non-integrin membrane-ECM interactions
Gene Ontology:
Molecular function: collagen binding; protein binding; protein tyrosine kinase collagen receptor activity; transmembrane receptor protein tyrosine kinase activity; ATP binding; protein kinase activity; protein tyrosine kinase activity
Biological process: collagen-activated tyrosine kinase receptor signaling pathway; peptidyl-tyrosine autophosphorylation; protein autophosphorylation; regulation of extracellular matrix disassembly; smooth muscle cell migration; smooth muscle cell-matrix adhesion; wound healing, spreading of cells; cell adhesion; cell surface receptor protein tyrosine kinase signaling pathway; positive regulation of neuron projection development; positive regulation of phosphatidylinositol 3-kinase/protein kinase B signal transduction
Cellular component: extracellular exosome; extracellular region; plasma membrane; receptor complex; membrane
Genetic constraint (gnomAD): Loss-of-function variants: 62 observed, 94.81 expected, observed/expected ratio (o/e) 0.65, 90% interval 0.53 to 0.81. The upper end of that interval is the gene's LOEUF score, 0.81, which puts it in group 3 of 6, group 1 being the genes least tolerant of losing a copy. Missense variants: 990 observed, 1,257.2 expected, observed/expected ratio (o/e) 0.79, 90% interval 0.75 to 0.83. Synonymous variants: 458 observed, 502.38 expected, observed/expected ratio (o/e) 0.91, 90% interval 0.84 to 0.99.
Homologues: Orthologues: macaque DDR1 (99% identical), chimpanzee DDR1 (99% identical), pig DDR1 (96% identical), dog DDR1 (96% identical), guinea pig DDR1 (94% identical), rat Ddr1 (94% identical), mouse Ddr1 (94% identical), rabbit DDR1 (71% identical), tropical clawed frog ddr1 (62% identical), zebrafish ddr1 (61% identical). Paralogues in human: DDR2 (52% identical), TIE1 (19% identical), INSR (19% identical), ROS1 (19% identical), IGF1R (19% identical), CSF1R (18% identical), NTRK2 (18% identical), TEK (18% identical), INSRR (18% identical), NTRK1 (18% identical), FGFR2 (18% identical), NTRK3 (18% identical), and 41 more.
Diseases named in the same sentence as DDR1 in open-access papers:
DDR1 is named in the same sentence as 215 diseases in open-access papers, as found by Europe PMC text mining. Sharing a sentence is not in itself a finding about the gene and the disease. The quoted sentences say what the papers report.
breast carcinoma (104 papers, 2011 to 2026). "The relation between somatic mutations and prognosis was determined and mutations in PIK3R1 and DDR1 were found to be associated with poor outcomes in HR+ breast cancer." (PMID 38977697, 2024). "Bioinformatic analysis of human breast cancer samples confirmed an association between DDR1 expression level and CD8A expression or CD8 T cell signatures in human patients." (PMID 35027528, 2022). "Upregulation of DDR1 promotes migration of breast cancer cells and DDR1 and DDR2 are associated with metastatic breast cancer." (PMID 33670586, 2021). "In contrast, high DDR1 expression is associated with a better relapse-free survival probability in breast cancer patients." (PMID 35004699, 2021). "It has been shown that higher DDR1 protein expression is associated with breast cancer, promoting proliferation by suppressing antitumor immunity." (PMID 34805157, 2021). "In breast cancer, this decrease of DDR1 expression has been linked to the increase of ZEB1 expression, which is involved in EMT, and which has been identified has a transcriptional repressor of DDR1 expression." (PMID 35004699, 2021). "DDR1 and 2 are frequently overexpressed in breast cancers and have recently been implicated in breast cancer metastasis." (PMID 31046834, 2019). "Decreased DDR1 expression has been associated with the epithelial to mesenchymal transition process in breast cancer, and its overexpression in aggressive basal-like breast cancer cells reduces their invasiveness in 3D cultures and in vivo." (PMID 31130862, 2019). "We have previously reported that, in breast cancer cells and in transfected fibroblasts, the collagen receptor DDR1 associates with the IGF-IR in an IGF-I dependent manner." (PMID 26655502, 2016). "It has been reported that DDR1 is overexpressed in high-grade brain, esophageal, and breast cancers, and high expression of DDR1 was associated with a significantly poorer survival in several cohorts of patients with brain, breast, and lung cancers." (PMID 21541037, 2011). "Indeed, previous studies have linked both RUNX1 and DDR1 to specific breast cancer phenotypes within specific subtypes." (PMID 40614729, 2025). "Heterogeneous nuclear ribonucleoprotein C could promote collagen fiber alignment and immune escape in breast cancer by activating vir like m6A methyltransferase associated-mediated TFAP2A/discoidin domain receptor tyrosine kinase 1 axis." (PMID 40813717, 2025). "Moreover, DDR1 is closely associated with the progression of hepatocellular carcinoma, lung cancer, and breast cancer." (PMID 40105492, 2025). "However, in postmenopausal breast cancer patients, the specific DDR1 kinase domain mutation R776W does correlate closely with a poor prognosis." (PMID 34805157, 2021). "Notably, DDR1 has been associated with chemoresistance in breast cancer, but also ovarian cancer or lymphatics." (PMID 32668815, 2020). "In studies with breast cancer cells, DDR1 was associated with induction of apoptosis." (PMID 32492656, 2020). "DDR1 expression has been associated with an increase in tumor invasion and aggressiveness of many human tumors, including esophageal cancer, gastric cancer, glioma, breast cancer, and lung cancer." (PMID 32582700, 2020). "This work suggested that DDR1 loss, by compromising cell adhesion and providing a cell growth advantage, contributes to the basal-like phenotype and consequently increases both the aggressiveness and metastatic potential of breast carcinomas." (PMID 31130862, 2019). "Using human breast cancer cells we found that DDR1 constitutively associated with the IGF-IR." (PMID 25840417, 2015). "Discoidin domain receptor 1 (DDR1) appears a potential candidate for collagen binding, which has recently been associated with malignancy, metastasis, and resistance in other tumor entities, such as breast cancer, gastric cancer, or pancreatic ductal adenocarcinomas." (PMID 31779287, 2019).
breast carcinoma (continued). "Decreased DDR1 expression has been associated with the EMT process in breast cancer, and its overexpression in aggressive basal-like breast cancer cells reduces their invasiveness in 3D cultures and in vivo, supporting an anti-migratory function of DDR1 in this cancer." (PMID 31130862, 2019). "Differently, in breast cancer, intβ1 and DDR1 converge on MAPK signaling underpinning a highly dynamic resistance mechanism." (PMID 41492134, 2026). "Conversely, in non-invasive luminal-like pancreatic cancer cells and invasive basal-like breast cancer cells, DDR1 inhibits tumor growth and promotes apoptosis." (PMID 40563472, 2025). "In breast cancer, stromal DDR1 promotes collagen deposition and tumor cell motility, fueling aggressive phenotypes." (PMID 40869052, 2025). "Activated by type I collagen, DDR1 upregulates CXCL5 in breast cancer cells, promoting the formation of neutrophil extracellular traps (NETs) and Treg infiltration, ultimately driving tumor growth." (PMID 40563472, 2025). "By targeting the suppression of DDR1, Nilotinib effectively blocked the migration of breast cancer cells." (PMID 40646517, 2025). "In breast cancer murine models, the combination of the DDR1 inhibitor 7 rh with palbociclib enhances tumor sensitivity to the latter." (PMID 40563472, 2025). "In breast cancer, DDR1 regulates several metabolism-related proteins, including MCT1, MCT4, hexokinase 2, PKM2, NRF-1, and mitochondrial complexes." (PMID 40563472, 2025). "In luminal breast cancer, type IV collagen drives glycolysis in tumor cells through DDR1-mediated MAPK signaling." (PMID 40563472, 2025). "Nilotinib, or other DDR1 inhibitors has been proven effective in preclinical cancer models include lung cancer, pancreatic cancer, ovarian cancer and breast cancer." (PMID 38388466, 2024). "In breast cancer dormant cells, the interaction of DDR1 with collagen I regulates self-renewal and metastatic reactivation via Signal Transducer and Activator of Transcription 3 (STAT3) activation." (PMID 39682261, 2024). "Another study confirmed the role of type III collagen and demonstrated that a recombinant humanized type III collagen inhibits cellular autophagy, proliferation, and migration through DDR1 and promotes breast cancer cell dormancy." (PMID 39682261, 2024). "Supporting this study, the use of PRTH-101 (monoclonal anti-DDR1 antibodies) in breast cancer mouse models disrupted stromal collagen organization, increasing immune infiltration and, consequently, survival." (PMID 39769286, 2024). "In breast cancer, the collagen receptor DDR1 inhibits T cells activation and infiltration by promoting collagen fiber alignment and further contributes to tumor immune escape." (PMID 38690275, 2024). "Some authors have described DDR1 as a tumor suppressor, as it induces apoptosis of basal-like breast cancer cells in 3D collagen I matrices and in luminal breast cancer cells in young collagen 1-enriched ECM." (PMID 37284199, 2023). "Together, our findings suggested that EFL1 protects against breast cancer liver metastasis in vivo by targeting DDR1-mediated immune infiltration." (PMID 37709489, 2023). "Together, these data suggested that DDR1 inhibition is required for EFL1 treating breast cancer liver metastasis." (PMID 37709489, 2023). "In conclusion, our results suggest that EFL1 protects against breast cancer liver metastasis through targeting DDR1-regulated immune infiltration." (PMID 37709489, 2023). "This study revealed the suppression effect of EFL1 on breast cancer liver metastasis, and highlights the potential role of inhibiting DDR1 in treating breast cancer." (PMID 37709489, 2023). "This suggested that DDR1-regulated immune infiltration was involved in the inhibitory effect of EFL1 in breast cancer liver metastasis." (PMID 37709489, 2023). "For example, DDR1 enhanced mammary tumor growth by regulating the production of interleukin-6 in mice." (PMID 37031216, 2023).
breast carcinoma (continued). "They demonstrate that breast cancer cell lines that lack DDR1 fail to engraft in immunocompetent mice, while growing at the same rate as wild-type tumors in immunodeficient mice." (PMID 35027528, 2022). "Using DEseq2 for differential expression analysis showed six protein kinases were transcriptionally upregulated in both patient basal-like breast cancers and three basal-like cell lines: DDR1, HER2, FRK, CDC42BPG, CDK19, and CDKL5." (PMID 34958800, 2022). "These also included new RTK drug targets for breast carcinoma, such as the discoidin domain receptor (DDR1), which is involved in the activation of cell proliferation, survival, ECM remodeling, migration and invasion pathways." (PMID 35760832, 2022). "In breast cancer cells, DDR1 increases Cdc42 activation and its specific guanine nucleotide-exchange factor (GEF) Tuba." (PMID 35309920, 2022). "The Zinc finger E-box-binding homeobox 1, for example, downregulates DDR1 expression in breast carcinoma cells and in the neurons of spinal dorsal horn after treatment with the chemotherapeutic drug oxaliplatin." (PMID 36249782, 2022). "Although DDR1 is ubiquitously expressed in epithelial cells, the expression level of DDR1 is significantly increased in tumor tissues such as colorectal cancer, breast cancer, lung cancer, glioma, ovarian cancer and esophageal cancer." (PMID 35140331, 2022). "Previous findings indicate that DDR1 is upregulated in colorectal cancer, breast cancer, lung cancer, glioma, ovarian cancer and esophageal cancer, and is involved in tumor invasion and metastasis." (PMID 35140331, 2022). "In three-dimensional collagen matrices, DDR1 promotes apoptosis of breast carcinoma cells through induction of the pro-apoptotic Bcl-2-interacting killer protein." (PMID 36249782, 2022). "For example, mammary glands from DDR1-null mice contain substantially more collagen in the adipose tissue and DDR1-null mammary tumors contain significantly more fibrillar collagen than tumors expressing DDR1." (PMID 36249782, 2022). "Inhibition of DDR1 expression can significantly enhance the chemosensitivity of breast cancer cells to genotoxic treatments." (PMID 34805157, 2021). "DARPP-32 (Dopamine- and cAMP-regulated phosphoprotein, Mr 32 kDa) binds to the IJXM domain of DDR1 and decreases collagen-stimulated invasion of breast cancer cells." (PMID 33917302, 2021). "In breast cancer, some studies showed crosstalk between DDR1 and the insulin and IGF receptors, IR-A and IGF-1R (Insulin like Growth Factor 1 Receptor)." (PMID 33917302, 2021). "The role of DDR1 in breast cancer proliferation or survival appears to depend, at least in part, on tumor type or culture method." (PMID 33917302, 2021). "Recently, in breast cancer, an inverse correlation was made between DDR1 expression by tumor cells and the level of CD4+ and CD8+ T-lymphocyte infiltration." (PMID 33917302, 2021). "DDR1 has been an attractive target for treating metastatic cancers like colorectal cancer, breast cancer, gastric cancer, pancreatic cancer, and lung cancer." (PMID 34837026, 2021). "In breast cancer cells, the binding of collagen I to DDR1 leads to the activation of the Cdc42-GEF Tuba, thereby inducing the formation of linear invadosomes, as well as promoting the activation of the proteolytic machinery and cell invasion." (PMID 33917302, 2021). "In this study, authors demonstrated that linear invadosomes can be formed in 3D COL1 matrix and that DDR1 depletion using DDR1 RNAi decrease breast cancer cell ability to invade 3D COL1 gel." (PMID 35004699, 2021). "In breast cancer, DDR1 activates the insulin-like growth factor I receptor (IGF-1R) to support several IGF-1R-mediated biological responses such as cell proliferation." (PMID 32582700, 2020). "In breast cancer, the interaction of collagen I with DDR1 expressed by tumour cells leads to the induction of stemness-like signalling through the activation of STAT3, which is crucial to mediate the metastatic outgrowth." (PMID 33037194, 2020).